TBX22 (T-box transcription factor 22)
Description:
Probable transcriptional regulator involved in developmental processes. This is major determinant crucial to palatogenesis.
Synonyms: ABERS; CLPA; CPX; TBXX; dJ795G23.1
Tractability: No criterion of Open Targets' tractability assessment is met for any kind of drug.
Gene: Protein-coding gene on chromosome X (80,014,753 to 80,031,908, forward strand). Ensembl gene ENSG00000122145.
Subcellular location: Nucleus
Gene Ontology:
Molecular function: DNA binding; protein binding; RNA polymerase II transcription regulatory region sequence-specific DNA binding; DNA-binding transcription factor activity, RNA polymerase II-specific; RNA polymerase II cis-regulatory region sequence-specific DNA binding; DNA-binding transcription factor activity; sequence-specific double-stranded DNA binding
Biological process: negative regulation of DNA-templated transcription; negative regulation of transcription by RNA polymerase II; cell fate specification; regulation of transcription by RNA polymerase II; positive regulation of DNA-templated transcription; regulation of DNA-templated transcription
Cellular component: nucleus; chromatin
Gene-disease validity (ClinGen):
ClinGen rates the evidence that TBX22 causes each of these diseases.
cleft palate with or without ankyloglossia, X-linked (X-linked): Definitive. X-linked cleft palate and ankyloglossia is a rare, genetic developmental defect during embryogenesis syndrome characterized by the association of complete, partial or submucous cleft palate and ankyloglossia.
Homologues: Orthologues: chimpanzee TBX22 (99% identical), macaque TBX22 (96% identical), rabbit TBX22 (83% identical), pig TBX22 (82% identical), rat Tbx22 (74% identical), mouse Tbx22 (72% identical), tropical clawed frog tbx22 (63% identical), Drosophila melanogaster mid (27% identical), Drosophila melanogaster H15 (26% identical), Caenorhabditis elegans mab-9 (25% identical), Drosophila melanogaster ocm (22% identical), Caenorhabditis elegans tbx-8 (17% identical), and 6 more. Paralogues in human: TBX15 (46% identical), TBX18 (43% identical), TBX20 (31% identical), MGA (28% identical), TBX1 (27% identical), TBX2 (27% identical), TBX4 (26% identical), TBX5 (25% identical), TBX3 (25% identical), TBX6 (25% identical), TBX10 (24% identical), TBR1 (23% identical), and 4 more.
Diseases named in the same sentence as TBX22 in open-access papers:
TBX22 is named in the same sentence as 24 diseases in open-access papers, as found by Europe PMC text mining. Sharing a sentence is not in itself a finding about the gene and the disease. The quoted sentences say what the papers report.
ankyloglossia (13 papers, 2004 to 2023). A developmental abnormality in which the bottom of the tongue is attached to the floor of the mouth. "Ankyloglossia is the most frequent disease presentation associated with TBX22 gene variants and is a minor anomaly, rarely considered important to report in patients or their family members." (PMID 35281813, 2022). "Loss-of-function mutations in human TBX22 cause a submucous cleft palate, a common birth defect that involves improper insertion of palatine muscle onto the hard palate and ankyloglossia (tongue-tie)." (PMID 33575564, 2020). "Mutations in the T-box containing transcription factor TBX22 cause ‘X-linked cleft palate including ankyloglossia’ (CPX)." (PMID 28877219, 2017). "First, one individual was found to present both OFC and TA likely due to a TBX22 missense mutation in a study based on a large cohort of patients with ankyloglossia and patients with sporadic isolated OFC." (PMID 27699475, 2016). "Mutations in the TBX22 gene are a well established cause of X-linked cleft palate with ankyloglossia as well as contributing to the prevalence of isolated cleft palate." (PMID 26323392, 2015). "Loss of murine Tbx22, which regulates intramembranous bone formation in the posterior hard palate, causes submucosal cleft palate with ankyloglossia in mice." (PMID 22436304, 2012). "After analysing the data from WES and identifying the loss of all coding exons of TBX22 in the proband with complete CP, we re-evaluated the family history and found ankyloglossia in individuals of all generations of the family, including putatively unaffected females." (PMID 36901693, 2023). "The role of TBX22 during palatogenesis was confirmed in experiments using Tbx22null mice, which presented with submucous CP, ankyloglossia, severely underdeveloped vomer, and choanal atresia, caused by reduced bone formation in the posterior hard palate due to impaired ossification." (PMID 35281813, 2022). "This may be due to the link of ankyloglossia to the X chromosome with variations in gene expression, in particular in the mutation of the T-box transcription factor gene (TBX22) during palatogenesis." (PMID 36231647, 2022). "For example, mutations in Tbx22 cause the human syndrome X-linked cleft palate and ankyloglossia." (PMID 14737183, 2004). "The phenotypic spectrum of subjects bearing TBX22 mutations can vary, even within the same family, from asymptomatic females to males or females with a bifid uvula, a cleft of the soft palate, or a complete cleft of the hard and soft secondary palate, along with ankyloglossia." (PMID 26323392, 2015). "Importantly, TBX22 was recently also implicated in cleft palate formation in humans in that up to 5% of children with non-syndromic cleft palate have mutations in TBX22, and TBX22 loss in humans is associated with X-linked cleft palate with ankyloglossia (CPX)." (PMID 22436304, 2012). "As a member of the T-box gene family, T-box transcription factor 22 (TBX22) mutations caused a high risk of incidence in several diseases, including non-syndromic cleft palate, hypodontia, and ankyloglossia." (PMID 33392186, 2020). "TBX22 knockout mice also show a submucous cleft palate and ankyloglossia; thus they resemble the phenotype observed in humans with TBX22 mutations." (PMID 33575564, 2020). "X-linked cleft palate with or without ankyloglossia (MIM#303400) is a rare disorder with a semidominant X-linked inheritance of mutations in TBX22." (PMID 36901693, 2023). "The loss of TBX22 in this family suggest the diagnosis of X-linked cleft palate with or without ankyloglossia." (PMID 36901693, 2023). "We validated the TBX22 deletion by qPCR and confirmed the variant in two males (proband and one of his affected cousins) and their mothers with ankyloglossia and without CP." (PMID 36901693, 2023).
ankyloglossia (continued). "Mutations in TBX22 are associated with X-linked cleft palate and ankyloglossia (OMIM # 303400), which is a disorder characterized by phenotypic heterogeneity ranging from ankyloglossia only to submucous cleft palate, bifid uvula or cleft of the soft and hard palate, all with or without tongue-tie." (PMID 36294409, 2022).
cleft palate (11 papers, 2010 to 2025). Cleft palate is a fissure type embryopathy that affects the soft and hard palate to varying degrees. "For example, TBX22 is associated with facial developmental defects such as a cleft lip and a cleft palate in humans, whereas C1QBP plays an essential role in regulating mitochondrial morphology, metabolism, and autophagy." (PMID 40565519, 2025). "The hypermethylation of Tbx22 was found to cause a decrease in gene expression and impaired palatogenesis with consequences of cleft palate." (PMID 36361518, 2022). "This raises the possibility that TBX22 loss in dogs makes them more susceptible to developing a cleft palate if other genes are mutated." (PMID 33575564, 2020). "Tbx22 encodes a T box-containing transcription factor that is mutated in families with X-linked cleft palate." (PMID 31596367, 2019). "Subsequently, we correlated our data to gene expression using qPCR, focusing on Fgf16 and Tbx22, previously reported to be associated with cleft palate formation." (PMID 31596367, 2019). "Additionally, Mn1 regulates maturation and function of calvarial osteoblasts and is an upstream regulator of Tbx22, a gene associated with murine and human cleft palate." (PMID 22436304, 2012). "Mutations in the frequently deleted gene TBX22 are linked to non-syndromic cleft palate, but TBX2 has no known role in tumorigenesis." (PMID 20126641, 2010).
X-linked cleft palate (11 papers, 2004 to 2023). "Mutations in TBX22 cause the rare X-linked syndrome ‘cleft palate with ankyloglossia’ (CPX; MIM 303400)." (PMID 22723972, 2012).
cleft lip (3 papers, 2020 to 2025). Congenital defect in the upper lip where the maxillary prominence fails to merge with the merged medial nasal prominences. "TBX22 has previously been shown to be associated with cleft lip and cleft palate." (PMID 39231932, 2024).
Hypodontia (2 papers, 2015 to 2020). The absence of five or less teeth from the normal series by a failure to develop. "More rarely, other craniofacial anomalies including cleft lip and hypodontia have also been related to TBX22 variants." (PMID 26323392, 2015).
orofacial cleft (2 papers, 2017 to 2023). A disorder of facial skeleton that is characterized by cleft lip and/or cleft palate that result in feeding, speech and hearing problems caused by failures during development. "Associations with KLHL4, EFNB1/PJA1, CPXCR1, TBX22, and BCOR were particularly noteworthy because they are involved in syndromes that feature orofacial clefts." (PMID 28877219, 2017).
autism spectrum disorder (1 paper, 2023). A spectrum of developmental disorders that includes autism, and Asperger syndrome. "It has been reported that the TBX22 gene is significantly associated with autism spectrum disorder in Vietnamese children." (PMID 38035272, 2023).
colorectal cancer (1 paper, 2024). A primary or metastatic malignant neoplasm that affects the colon or rectum. "X‐linked FLNA, TBX22, KIAA2022, IRS4, PCDH11X, GPR112, and F8 have been proposed as cancer‐related genes in colorectal cancer." (PMID 38827026, 2024). "The X‐linked cancer‐related genes FLNA, TBX22, KIAA2022, IRS4, PCDH11X, and GPR112 are connected to colorectal cancer." (PMID 38827026, 2024).
emphysema (1 paper, 2023). "This included different directions of effect among one variant for lung function near ITM2A and four variants for emphysema near TAB3, TBX22, GUCY2F, and FMR1-AS1." (PMID 36726148, 2023).
ependymoma (1 paper, 2024). A WHO grade II, slow growing tumor of children and young adults, usually located intraventricularly. "BST1, FLG, KANK4, and SHISA9 were significantly higher expressed in SP-EPN subtype A compared to all other ependymomas, whereas AK5, CFTR, RASSF6, and TBX22 showed high expression in subtype B." (PMID 38265489, 2024).
Holt-Oram syndrome (1 paper, 2020). Holt-Oram syndrome (HOS) is the most common form of heart-hand syndrome and is characterized by skeletal abnormalities of the upper limbs and mild-to-severe congenital cardiac defects. "In humans, these heterozygous conditions can lead to syndromes, including Holt-Oram Syndrome (HOS, TBX5), ulna mammary syndrome (UMS, TBX3), DiGeorge syndrome (TBX1), spondylocostal dysostosis (TBX6) and cleft palate and ankyloglossia (TBX22)." (PMID 32855167, 2020).
tumor (3 papers, 2019 to 2024). "We also found that TBX22 expression was negatively associated with advanced clinicopathological characteristics, including larger tumor size, LNM, higher disease stage, and extrathyroidal extension." (PMID 33392186, 2020). "Based on functional enrichment analysis, we explored the link between TBX22 and tumor immunity-associated molecular features." (PMID 33392186, 2020). "As a validation, we found that TBX22 was also associated with tumor size and LNM in our local cohort." (PMID 33392186, 2020). "Our further analysis of PTC profiles of the local cohort validated that the expression of TBX22 was significantly associated with tumor size (p = 0.012) and LNM (p = 0.0051)." (PMID 33392186, 2020). "In the TCGA cohort, the mRNA level of TBX22 in PTC patients was significantly associated with tumor size (p = 1.6e-05), nodal metastasis (p = 1.9e-06), extrathyroidal extension (p = 7.1e-08), and disease stage (p = 0.003)." (PMID 33392186, 2020). "Firstly, more local tumor samples are needed to verify the relationship between TBX22 and the clinical characteristics and confirm its predictive performance as a biomarker in PTC." (PMID 33392186, 2020). "Our study is the first to identify the expression level and the relationship with the clinicopathological and molecular features, tumor-infiltrating, cancer immunity cycle, and functional effects of TBX22 in PTC." (PMID 33392186, 2020). "The present findings disclose that TBX22, as an immune microenvironment-related biomarker, could be an important tumor suppresser gene and might inform the management of PTC patients better." (PMID 33392186, 2020). "These well-reproductive results revealed that TBX22 might have intrinsic roles in tumor immunity and PTC progression." (PMID 33392186, 2020). "Together, these findings suggest that TBX22 exerts a considerable tumor-suppressor effect in PTC." (PMID 33392186, 2020). "TBX22, a tumor suppressor gene regulating papillary thyroid carcinoma (PTC), suppresses tumor proliferation and migration." (PMID 38965548, 2024). "To validate the transcription level of TBX22 in our local PTC patients, we performed qRT-PCR of 79 pairs of tumor samples and adjacent normal thyroid tissues, and TBX22 was downregulated in PTC tissues compared with that in adjacent normal tissues (p < 0.0001)." (PMID 33392186, 2020).
cancer (2 papers, 2019 to 2020). A tumor composed of atypical neoplastic, often pleomorphic cells that invade other tissues. "Functional enrichment analysis revealed that cancer-related pathways and immune progress were closely associated with TBX22 in PTC." (PMID 33392186, 2020). "Patients who have lower TBX22 expression showed higher anticancer immunity scores in different steps of the cancer immunity cycle." (PMID 33392186, 2020). "In summary, TBX22low state may be associated with active anticancer immune response, and TBX22 had a negative role in the cancer immunity cycle." (PMID 33392186, 2020). "T-box transcription factor 22 (TBX22) is a phylogenetically conserved family member that has not been widely characterized in cancers." (PMID 33392186, 2020).
TBX22 also shares sentences with these, for which no sentence is quoted: infection (5 papers); choanal atresia (2); Abruzzo-Erickson syndrome (1); autism (1); DiGeorge syndrome (1); Lyme borreliosis (1); Papillary Thyroid Carcinoma (1); schizophrenia (1); thyroid cancer (1); X-linked deafness (1); X-linked intellectual disability (1).